TAMALIN (trafficking regulator and scaffold protein tamalin)
Description:
Plays a role in intracellular trafficking and contributes to the macromolecular organization of group 1 metabotropic glutamate receptors (mGluRs) at synapses.
Synonyms: GRASP
Tractability: Antibody: UniProt places it where antibodies can reach, with medium confidence; its Gene Ontology location is reachable by antibodies, with medium confidence. PROTAC: ubiquitination databases record sites on it.
Gene: Protein-coding gene on chromosome 12 (52,006,946 to 52,015,889, forward strand). Ensembl gene ENSG00000161835.
Subcellular location: Cytoplasm, perinuclear region; Cell membrane; Postsynaptic cell membrane
Subcellular location (Human Protein Atlas): Vesicles; Nuclear bodies
Gene Ontology:
Molecular function: protein binding; identical protein binding; PDZ domain binding; small GTPase binding
Biological process: signal transduction; regulation of postsynaptic neurotransmitter receptor internalization
Cellular component: plasma membrane; postsynaptic membrane; glutamatergic synapse; perinuclear region of cytoplasm; postsynaptic density
Genetic constraint (gnomAD): Loss-of-function variants: 11 observed, 31 expected, observed/expected ratio (o/e) 0.35, 90% interval 0.22 to 0.59. The synonymous counts are far from expectation, so gnomAD's model fits this gene poorly and the ratio says little. Missense variants: 470 observed, 381.07 expected, observed/expected ratio (o/e) 1.23, 90% interval 1.14 to 1.33. Synonymous variants: 266 observed, 178.81 expected, observed/expected ratio (o/e) 1.49, 90% interval 1.35 to 1.65.
Homologues: Orthologues: chimpanzee TAMALIN (99% identical), macaque TAMALIN (97% identical), pig TAMALIN (93% identical), rat Tamalin (91% identical), mouse Tamalin (91% identical), dog TAMALIN (89% identical), rabbit TAMALIN (88% identical), guinea pig TAMALIN (73% identical), tropical clawed frog tamalin (53% identical), zebrafish tamalin (46% identical), Drosophila melanogaster ssp6 (23% identical), Caenorhabditis elegans gras-1 (15% identical). Paralogues in human: CYTIP (32% identical).
Diseases named in the same sentence as TAMALIN in open-access papers:
TAMALIN is named in the same sentence as 22 diseases in open-access papers, as found by Europe PMC text mining. Sharing a sentence is not in itself a finding about the gene and the disease. The quoted sentences say what the papers report.
schizophrenia (2 papers, 2018 to 2022). A major psychotic disorder characterized by abnormalities in the perception or expression of reality. "TAMALIN, a trafficking molecule of Metabotropic glutamate receptor 5 (mGluR5), showed increased expression in the hippocampal region of individuals with schizophrenia." (PMID 36061196, 2022).
TAMALIN also shares sentences with these, for which no sentence is quoted: cancer (6 papers); tumor (4); colorectal cancer (3); adenoma (2); asthma (2); infection (2); Alzheimer disease (1); Anorexia (1); bladder cancer (1); breast carcinoma (1); Cirrhosis (1); cystic fibrosis (1); diabetes (1); glioma (1); infectious disease (1); liver disease (1); lung carcinoma (1); obstructive lung disease (1); periodontitis (1); prostate carcinoma (1); Stroke (1).